MT-TP (mitochondrially encoded tRNA-Pro (CCN))
Diseases named in the same sentence as MT-TP in open-access papers (continued):
Sharing a sentence is not in itself a finding about the gene and the disease.
metabolic syndrome X (1 paper, 2022). "For example, in the subnetwork for metabolic syndrome X, pathogenesis genes AGTR2 and ADRA1A are at the top hierarchical layer for chemokine signaling, while IRF1, MXZB1, MTTP, and CNTC are at the top layer in cytokine signaling." (PMID 35404985, 2022).
nasopharyngeal carcinoma (1 paper, 2024). A carcinoma arising from the nasopharyngeal epithelium. "Mutations in MT-TP gene 1603T > C and 16519T > C were found in patients with nasopharyngeal carcinoma and ovarian cancer." (PMID 39802950, 2024).
tumor (4 papers, 2018 to 2024). "Since our multi-omics analysis showed that lipid metabolism plays an important role in tumor progression, we focused further on the analysis of Lomitapide, an inhibitor of microsomal triglyceride-transfer protein (MTTP), which could inhibit tumor growth in all LEGOs." (PMID 38273014, 2024).
metabolic disease (2 papers, 2013 to 2023). A congenital disorder (due to inherited enzyme abnormality) or acquired (due to failure of a metabolically important organ) disorder resulting from an abnormal metabolic process. "In this work we characterize two other unrelated patients affected by this metabolic disorder and we identify a novel mutation in MTTP gene leading to a non functional protein." (PMID 23556456, 2013). "ABL is a rare autosomal recessive metabolic disorder characterized by complete absence of plasma apo B-containing lipoproteins that results from mutations in MTTP gene." (PMID 23556456, 2013).
infection (1 paper, 2022). The state of being infected such as from the introduction of a foreign agent such as serum, vaccine, antigenic substance or organism. "The association analysis of the group of patients with chronic hepatitis C provides useful information on the effect of HCV genotype 3 infections combined with the -493G/T and I128T SNPs in the MTTP gene on hepatic steatosis." (PMID 36027755, 2022).
mitochondrial disease (1 paper, 2016). "We report 5 adult patients with mitochondrial disease due to different mutations in the MT-TP gene with a predominantly myopathic phenotype." (PMID 27536729, 2016). "We identified 5 adult patients with mitochondrial disease due to mutations in the MT-TP gene; their clinical, histochemical, and genetic data are summarized in table e-1." (PMID 27536729, 2016).
MT-TP also shares sentences with these, for which no sentence is quoted: hypobetalipoproteinemia (4 papers); Ataxia (2); diabetes (2); glioma (2); Obesity (2); retinitis pigmentosa (2); acanthocytosis (1); anemia (1); Arthritis (1); astrocytoma (1); cardiovascular diseases (1); Central hypothyroidism (1); colorectal cancer (1); cryptogenic cirrhosis (1); deafness (1); dilated cardiomyopathy (1); gastric cancer (1); genotype (1); glioblastoma (1); Hypercholesterolemia (1); lipid metabolism disorders (1); liver fibrosis (1); male infertility (1); myoclonic epilepsy (1); myopathy (1); neuropathy (1); Niemann-Pick disease, type C1 (1); ovarian carcinoma (1); Parkinsonism (1); polycystic kidney disease (1).
A further 1 disease shares a sentence with MT-TP in 1 paper.